RO60 (Ro60, Y RNA binding protein)
Description:
RNA-binding protein that binds to misfolded non-coding RNAs, pre-5S rRNA, and several small cytoplasmic RNA molecules known as Y RNAs. Binds to endogenous Alu retroelements which are induced by type I interferon and stimulate porinflammatory cytokine secretion. Regulates the expression of Alu retroelements as well as inflammatory genes. May play roles in cilia formation and/or maintenance (By similarity).
Synonyms: RoRNP; SSA2; TROVE2
Tractability: PROTAC: ubiquitination databases record sites on it.
Gene: Protein-coding gene on chromosome 1 (193,059,445 to 193,091,777, forward strand). Ensembl gene ENSG00000116747.
Subcellular location: Cytoplasm
Subcellular location (Human Protein Atlas): Cytosol; Primary cilium; Nuclear bodies; Nucleoplasm
Gene Ontology:
Molecular function: RNA binding; U2 snRNA binding
Biological process: cellular response to interferon-alpha; regulation of gene expression; transcription by RNA polymerase III
Cellular component: cytoplasm; cytosol; ribonucleoprotein complex; nucleus
Genetic constraint (gnomAD): Loss-of-function variants: 17 observed, 49.09 expected, observed/expected ratio (o/e) 0.35, 90% interval 0.24 to 0.52. The upper end of that interval is the gene's LOEUF score, 0.52, which puts it in group 2 of 6, group 1 being the genes least tolerant of losing a copy. Missense variants: 493 observed, 610.01 expected, observed/expected ratio (o/e) 0.81, 90% interval 0.75 to 0.87. Synonymous variants: 193 observed, 207.51 expected, observed/expected ratio (o/e) 0.93, 90% interval 0.83 to 1.05.
Homologues: Orthologues: chimpanzee RO60 (99% identical), macaque RO60 (99% identical), dog RO60 (97% identical), pig RO60 (93% identical), rabbit RO60 (93% identical), guinea pig RO60 (90% identical), mouse Ro60 (90% identical), rat Ro60 (90% identical), tropical clawed frog ro60 (78% identical), zebrafish ro60 (54% identical), Caenorhabditis elegans rop-1 (40% identical), Drosophila melanogaster CG10803 (19% identical).
Diseases named in the same sentence as RO60 in open-access papers:
RO60 is named in the same sentence as 67 diseases in open-access papers, as found by Europe PMC text mining. Sharing a sentence is not in itself a finding about the gene and the disease. The quoted sentences say what the papers report.
systemic lupus erythematosus (64 papers, 2006 to 2026). An autoimmune multi-organ disease typically associated with vasculopathy and autoantibody production. "Pathogenic bacteria were detected in lupus gut with bacterial ribonucleoprotein ortholog induce production of anti-Ro60 antibodies." (PMID 36979632, 2023). "Colonization of Bacteroides thetaiotaomicron in lupus mice was found to enhance the expression of Ro60 antigen followed by deposition of immune complex causing lupus nephritis." (PMID 36979632, 2023). "Alu elements have also gained interest in lupus research due to the association of Alu-derived RNA with Ro60, a well-recognized SLE autoantigen." (PMID 33669709, 2021). "Alu elements were found associated with the Ro60 immune complexes from the blood of individuals with lupus, and autoantibodies against LINE-1 ORF1 are characteristic of a population of SLE patients with severe and active disease and higher type I IFN score." (PMID 33888553, 2021). "Antibodies against Ro52 have been described in patients with different autoimmune diseases, such as systemic lupus erythematosus and Sjögren’s syndrome, that are often associated with anti-Ro60 antibodies." (PMID 26673754, 2015). "Antibodies against Ro-52 have been described in patients with a broad spectrum of autoimmune disease, most commonly in association with anti-Ro-60 in systemic lupus erythematosus and Sjogrens syndrome." (PMID 19267890, 2009). "Because well-known lupus autoantigens like RO60 associate with ORF1p in macromolecular assemblies, together with many other RNA-binding proteins, we tested whether these other proteins are also recognized by IgG autoantibodies in SLE patients." (PMID 39606792, 2023). "Y RNAs associate with the Ro60 protein, a major autoantigen triggering autoimmunity in lupus." (PMID 31152666, 2019). "In solid phase binding assays, biotinylated Fe3+ Hb interacted with the lupus-associated autoantigens Sm, Ro52, Ro60, and RNP68k to varying degrees; interaction was significantly diminished upon competition with unlabeled Fe3+ Hb, a strong indicator of the specificity of binding." (PMID 28694810, 2017). "Anti-Ro60 antibodies can be positive in several autoimmune diseases, including Sjögren’s syndrome, systemic sclerosis, myositis, and lupus." (PMID 40142449, 2025). "Since anti-Ro antibodies are thought to contribute to epitope spreading, microbes with Ro60 orthologs are worth investigating, particularly for their roles in the initial stages of lupus development." (PMID 40142449, 2025). "Regulation of RNA Pol III and thus Y RNA expression by ADAR1 provides also an unexpected piece to the puzzle of onset of autoimmune diseases such as systemic lupus erythematosus and Sjögren's syndrome in which the role of Ro60 and ADAR has been proposed." (PMID 38844344, 2024). "Ro60 autoantibodies serve as diagnostic markers for various autoimmune diseases, including Sjögren’s disease (SjD) and systemic lupus erythematosus (SLE), and they may also act as predictive markers for anti-drug antibody responses among rheumatic patients." (PMID 39062948, 2024). "Evidence that commensal orthologs of the human autoantigen Ro60 function as triggers of autoimmunity in lupus." (PMID 38125641, 2023). "Propionibacterium propionicum and Bacteroides thetaiotaomicron, two of the identified commensal microorganisms, were regarded to activate Ro60-specific CD4+ memory T cells in lupus patients." (PMID 37621873, 2023). "The first is the protein 60 kDa (Ro60), the autoantigen most commonly found in systemic autoimmune diseases such as Systemic lupus erythematosus (SLE) and Sjögren’s syndrome." (PMID 35055069, 2022). "A majority of cases are associated with maternal antibodies against Ro (SSA)−52, Ro-60 or La (SSB)−48, as seen in systemic lupus erythematosus (SLE), or autoantibodies associated with Sjogren's syndrome." (PMID 34434978, 2021).
systemic lupus erythematosus (continued). "Antibodies against Ro60/SSA/TROVE2, an evolutionarily conserved RNA-binding protein, are present in more than 50% of lupus patients." (PMID 34335588, 2021). "Human Ro60 autoantigen–specific CD4 memory T cell clones from lupus patients react to Bacteroides thetaiotaomicron containing Ro60 orthologs." (PMID 34335588, 2021). "Cross-reactivity between Ro60 and EBV nuclear antigen-1 (EBNA-1) protein produced after EBV infection has been proposed as a mechanism for the progressive development of anti-Ro60 antibody in lupus patients." (PMID 34335588, 2021). "In systemic lupus erythematosus, seropositive autoantibodies against Ro52, Ro60, and DNA were detectable on average 10 or more years before diagnosis." (PMID 33763057, 2021). "Lysates of B. theta bind to serum from anti-Ro60-positive patients with systemic lupus erythematosus." (PMID 33187522, 2020). "Some human commensals produce proteins similar to human Ro60 and, although these bacteria are found in both healthy donors and lupus patients, only lupus patients have antibodies and T cells reactive with human Ro60 and microbial Ro60 orthologs." (PMID 33424846, 2020). "We highlight that editing regulation by Ro60 is consistent with the global up-regulation of RNA editing in systemic lupus erythematosus." (PMID 30652130, 2019). "Y-RNAs were initially discovered as RNA components of circulating ribonucleoprotein (RNP) autoantigens Ro60 and La in serum from lupus patients." (PMID 30697216, 2018). "Y RNAs were first identified as non-coding RNAs bound by the Ro60 protein, a common 60 kDa antigen detected by antibodies from patients with the autoimmune diseases Systemic Lupus Erythematosus and Sjögren's syndrome." (PMID 26159929, 2015). "Sera from patients with myositis or systemic lupus erythematosus who have anti-Jo-1 and/or anti-Ro52/anti-Ro60 (anti-SSA) autoantibodies have IFN-α-inducing property." (PMID 25301447, 2014). "Only sMER showed significant associations with lupus-specific anti-dsDNA, anti-Sm, anti-ribonucleoprotein (anti-RNP) and anti-Ro60 autoantibodies." (PMID 24325951, 2013). "In summary, the most significant differences observed between mothers of groups I and II were in lupus mothers of group I, who possessed a significantly higher frequency of IgG antibodies to Ro52 peptides 107–122 and 277–292 and to Ro60 peptide 21–41." (PMID 16356190, 2006). "In turn, these autoantigens are associated with different autoimmune processes: anti-Ro60 antibodies are mainly detected in systemic lupus erythematosus (SLE) and Sjögren syndrome (SS), while anti-Ro52 antibodies are present in a number of autoimmune diseases ranging from SLE and SS to IIM." (PMID 38895121, 2024). "YRNAs are particularly associated with autoimmune conditions, having been initially identified as components of the RoRNP (Ro60 RNA-binding protein ribonucleoprotein) complex observed in the serum of individuals with systemic lupus erythematosus (SLE) and Sjögren's syndrome." (PMID 37662051, 2023). "Similarly, some peptides produced by Bacteroides thetaiotaomicron and Roseburia intestinalis show similarity with human Ro60 and β2-glycoprotein I, which can trigger lupus-like symptoms." (PMID 34090383, 2021). "Autoantibodies against the RNA binding protein Ro60 are produced by a majority of lupus patients." (PMID 32849620, 2020). "Together, this model suggests that there is selective cross-reactivity between a Ro60 ortholog from commensal bacteria and human Ro60, further emphasizing how infection may play a role in triggering autoimmunity in lupus." (PMID 31781110, 2019). "Understanding the mechanisms of antigenicity of Ro52 and Ro60 may shed light on the pathogenesis of systemic lupus erythematosus, SS and other autoimmune diseases." (PMID 29463848, 2018). "Among lupus-specific autoantibodies, sMer levels showed the strongest association with anti-Ro60 antibodies, particularly in the absence of a concomitant anti-La positivity." (PMID 24325951, 2013).
systemic lupus erythematosus (continued). "Therefore, the intestinal microbiota containing sequences akin to human Ro60 epitopes may contribute to SLE by exacerbating pathological damages and dysregulated autoimmune responses in lupus-susceptible individuals." (PMID 38765017, 2024). "Furthermore, CD4 memory T cell clones from lupus patients could be stimulated by both human Ro60 and bacterial orthologous Ro60, supporting T cell cross-reactivity." (PMID 35742974, 2022). "Autoantibodies against the 60 kDa Ro (Ro60)/SSA ribonucleoprotein (TROVE2), which is a common member of extractable nuclear antigens and frequent target of humoral immunity, are usually detected in autoimmune diseases such as primary Sjogren's syndrome, systemic lupus erythematosus, and RA." (PMID 33763493, 2021). "Anti-Ro60 antibodies occur in many patients with systemic lupus erythematosus (SLE), an autoimmune disease characterized by interferon activation, autoantibodies and multi-organ tissue destruction." (PMID 30652130, 2019). "However, as mentioned in the “Intestinal dysbiosis in Systemic Lupus Erythematosus” section, this microbe is thought to contribute to SLE pathogenesis through the cross-reactivity of T cells between the commensal Ro60 ortholog and the human Ro60 protein." (PMID 40142449, 2025). "Experience from lupus patients after anti-CD19 CAR-T therapy demonstrates a marked decrease in anti-histone and anti-dsDNA titers, while Ro60 remains unchanged." (PMID 40746557, 2025). "Ro60 was originally identified as a soluble antigen targeted by autoantibodies from patients with autoimmune rheumatic diseases; systemic lupus erythematosus (SLE) and Sjögren’s syndrome." (PMID 38308367, 2024). "It was found early that the lupus autoantigen Ro60 cross-reacted with the Ebstein-Barr virus nuclear antigen-1 (EBNA-1), suggesting that lupus humoral autoimmunity was initiated via molecular mimicry of EBNA-1 and Ro60 antigens." (PMID 31575045, 2019). "The SS-A1/Ro52, SS-A2/Ro60 and SS-B/La antigens are the targets of certain antinuclear autoantibodies (ANA) characteristically detected in Sjögren syndrome (SS) and systemic lupus erythematosus (SLE)." (PMID 31435505, 2017). "Anti-SSA/Ro60 and anti-SSB/La are essential serological biomarkers for rheumatic diseases, specifically Sjögren’s syndrome (SS) and systemic lupus erythematosus (SLE)." (PMID 27184054, 2016). "While autoantibodies to four of the six Sjögren’s/systemic lupus erythematosus antigens tested (RNP-A, RNP-70, Sm-D3, and La), were also seronegative, a few patients exhibited elevated autoantibodies against Ro52 and Ro60." (PMID 26482341, 2015). "CIMT scores were highest in the SLE subset with anti-Ro60 autoantibodies compared with all other lupus subsets and normal controls." (PMID 39055110, 2023). "Nevertheless, we found that sMer, but not sAxl, was significantly associated with lupus-specific humoral autoimmune responses, which were characterized by production of anti-dsDNA, anti-Sm, anti-RNP and anti-Ro60 autoantibodies." (PMID 24325951, 2013). "Some researchers suggest that anti-Ro60 abs are sufficient to diagnose pSS, while anti-La/SSB abs are heterogenous and may be present in other autoimmune diseases, such as systemic lupus erythematosus (SLE), neonatal lupus erythematosus (NLE), and inflammatory myositis as well as pSS." (PMID 39364411, 2024). "Compared to matched healthy controls, plasma levels of sMer, but not sAxl, were found to be higher in patients with active lupus (SLEDAI score ≥6), active BILAG renal score and anti-dsDNA and anti-Ro60 positivity." (PMID 24325951, 2013).
Sjögren’s syndrome (44 papers, 2006 to 2026). "To date, diagnosis of SjS relies on an objective sicca syndrome associated with the positivity of at least one of the following criteria: i) anti-SSA/Ro60 autoantibodies, ii) lymphocytic infiltration of salivary glands." (PMID 37529039, 2023). "The same analysis applied to the other diseases showed that in Sjögren’s syndrome there are two antibodies that are significantly associated with: anti-Ro60 and anti-Ro52 (p=0.0001 and 0.001, respectively)." (PMID 36564813, 2022). "However, it is important to maintain anti-La antibodies in the diagnostic profile because when anti-Ro60 and anti-La are combined, specificity for Sjögren’s syndrome is high (99.3% vs. controls and 93.4% vs. SLE)." (PMID 36564813, 2022). "For instance, the RNA-binding protein Ro60, a common target of autoantibody responses in patients with SLE and Sjogren’s syndrome, shares sequences akin to human Ro60 epitopes and is found in gut microorganisms such as Bacteroides thetaiotaomicron." (PMID 40005809, 2025). "For example, it is unclear how autoantibodies against Ro52 and Ro60 proteins in Sjögren’s syndrome act as biomarkers for salivary gland dysfunction and why the ubiquitous t-RNA synthetases are targets of autoantibodies in myositis." (PMID 33763057, 2021). "In the case of Sjögren’s syndrome, autoantibodies against Ro52 and Ro60 are often detected in the earliest retrospective serum sample available and can appear up to 18 years before diagnosis." (PMID 33763057, 2021). "In the Ro52+Ro60+ group, systemic lupus was frequent (41.5%), as was primary Sjögren's syndrome (39.2%)." (PMID 30915082, 2019). "Primary Sjögren's syndrome in the Ro52+Ro60+ group was, respectively, four and ten times more prevalent than in the Ro52-Ro60+ and Ro52+Ro60 group (p < 10−4)." (PMID 30915082, 2019). "Patients with both Ro52 and Ro60 Ab were far more likely to be diagnosed with primary Sjögren's syndrome or in a less remarkable fashion, systemic lupus." (PMID 30915082, 2019). "In the Ro52+Ro60+, primary Sjögren Syndrome was the most likely (OR 4.2 95% CI [2.1–8.3] p < 10−4), especially in patients Ro52+Ro60+La+." (PMID 30915082, 2019). "In Sjögren's syndrome, patients in the Ro52+Ro60+ group were more likely to have hypergammaglobulinemia (p = 0.002)." (PMID 30915082, 2019). "The contribution of the formation of HNE adducts to the modification of self antigens, such as SS-A2/Ro60, in Sjögren's syndrome was explored by Scofield and coworkers." (PMID 24027536, 2013). "Moreover, immunization with high-level HNE-modified SS-A2/Ro60 was associated with weaker antibody responses to unmodified SS-A2/Ro60 and SS-B/La, reduction of salivary flow and lymphocytic infiltration of salivary glands, suggesting a Sjögren's syndrome-like condition." (PMID 24027536, 2013). "Antibodies to SSA antigen (Ro52/Ro60) were historically described as a marker for Sjögren syndrome and systemic lupus erythematosus." (PMID 22567412, 2012). "The Ro/La cluster observed here in SLE patients is similar to that of Sjögren's Syndrome, in which 75% of the patients also show autoantibodies against Ro52, Ro60 and La." (PMID 22363785, 2012). "Antibodies to the 52 kDa protein Ro-52 were first described in 1988 in addition to antibodies to Ro-60 and La in the serum of patients with Sjogrens syndrome (SS)." (PMID 19267890, 2009). "Sjögren's Syndrome (SjS) has historically been associated with classical anti-Ro60/SSA, Ro52/SSA and La/SSB, however they are lacking in one third of the patients, which induces delays in diagnosis, and their disease-contributing role is debated." (PMID 42310390, 2026). "Ro60 is an RNA binding protein that negatively regulates Alu transcription; in Sjögren’s syndrome, the absence of Ro60 induces Alu re-expressed and causes the upregulation of IFN-I genes." (PMID 36768929, 2023). "Anti-SSA/Ro60 (anti-SSA) antibodies represent a cornerstone in primary Sjögren’s syndrome (pSS)." (PMID 35011983, 2022).